PSMC5 (proteasome 26S subunit, ATPase 5)
Description:
Component of the 26S proteasome, a multiprotein complex involved in the ATP-dependent degradation of ubiquitinated proteins. This complex plays a key role in the maintenance of protein homeostasis by removing misfolded or damaged proteins, which could impair cellular functions, and by removing proteins whose functions are no longer required. Therefore, the proteasome participates in numerous cellular processes, including cell cycle progression, apoptosis, or DNA damage repair. PSMC5 belongs to the heterohexameric ring of AAA (ATPases associated with diverse cellular activities) proteins that unfolds ubiquitinated target proteins that are concurrently translocated into a proteolytic chamber and degraded into peptides.
Synonyms: TRIP1; SUG1; p45/SUG; TBP10; p45; S8; SUG-1; RPT6; YKNS
Tractability: Small molecule: an approved drug acts on it; a structure with a bound ligand is known; a high-quality ligand is known. Antibody: the Human Protein Atlas places it where antibodies can reach. PROTAC: ubiquitination databases record sites on it; its protein half-life has been measured.
Target class: Enzyme
Gene: Protein-coding gene on chromosome 17 (63,827,152 to 63,832,244, forward strand). Ensembl gene ENSG00000087191.
Subcellular location: Cytoplasm; Nucleus
Subcellular location (Human Protein Atlas): Cytosol; Plasma membrane
Pathways (Reactome):
Immune System: AMPK-induced ERAD and lysosome mediated degradation of PD-L1(CD274); Activation of NF-kappaB in B cells; Antigen processing: Ubiquitination & Proteasome degradation; CLEC7A (Dectin-1) signaling; Cross-presentation of soluble exogenous antigens (endosomes); Dectin-1 mediated noncanonical NF-kB signaling; Downstream TCR signaling; ER-Phagosome pathway; FCERI mediated NF-kB activation; GSK3B-mediated proteasomal degradation of PD-L1(CD274); Interleukin-1 signaling; NIK-->noncanonical NF-kB signaling; SPOP-mediated proteasomal degradation of PD-L1(CD274); TNFR2 non-canonical NF-kB pathway
Cell Cycle: APC/C:Cdc20 mediated degradation of Securin; APC/C:Cdh1 mediated degradation of Cdc20 and other APC/C:Cdh1 targeted proteins in late mitosis/early G1; Autodegradation of Cdh1 by Cdh1:APC/C; Autodegradation of the E3 ubiquitin ligase COP1; Cdc20:Phospho-APC/C mediated degradation of Cyclin A; FBXL7 down-regulates AURKA during mitotic entry and in early mitosis; G2/M Checkpoints; SCF(Skp2)-mediated degradation of p27/p21; SCF-beta-TrCP mediated degradation of Emi1; Separation of Sister Chromatids; The role of GTSE1 in G2/M progression after G2 checkpoint; Ubiquitin-Mediated Degradation of Phosphorylated Cdc25A; Ubiquitin-dependent degradation of Cyclin D
Signal Transduction: Asymmetric localization of PCP proteins; Degradation of AXIN; Degradation of DVL; Degradation of GLI1 by the proteasome; Degradation of GLI2 by the proteasome; Degradation of beta-catenin by the destruction complex; GLI3 is processed to GLI3R by the proteasome; Hedgehog 'on' state; Hedgehog ligand biogenesis; MAPK6/MAPK4 signaling; Negative regulation of NOTCH4 signaling; Regulation of PTEN stability and activity; Regulation of RAS by GAPs
and 27 more pathways
Gene Ontology:
Molecular function: DNA-binding transcription factor binding; general transcription initiation factor binding; protein binding; thyrotropin-releasing hormone receptor binding; transcription factor binding; proteasome-activating activity; ATP binding; ATP hydrolysis activity; signaling receptor binding; TBP-class protein binding
Biological process: proteasome-mediated ubiquitin-dependent protein catabolic process; regulation of transcription by RNA polymerase II; cellular response to type I interferon; negative regulation of programmed cell death; positive regulation of DNA-templated transcription; positive regulation of proteasomal protein catabolic process; proteasomal protein catabolic process; regulation of proteasomal protein catabolic process; response to oxidative stress; positive regulation of inclusion body assembly
Cellular component: blood microparticle; cytoplasm; cytoplasmic vesicle; cytosol; extracellular exosome; membrane; nucleus; plasma membrane; proteasome complex; nucleoplasm; proteasome accessory complex; synaptic vesicle; cytosolic proteasome complex; inclusion body; nuclear proteasome complex; proteasome regulatory particle
Genetic constraint (gnomAD): Loss-of-function variants: 11 observed, 47.19 expected, observed/expected ratio (o/e) 0.23, 90% interval 0.15 to 0.39. The upper end of that interval is the gene's LOEUF score, 0.39, which puts it in group 1 of 6, group 1 being the genes least tolerant of losing a copy. Missense variants: 229 observed, 518.75 expected, observed/expected ratio (o/e) 0.44, 90% interval 0.4 to 0.49. Synonymous variants: 206 observed, 194.89 expected, observed/expected ratio (o/e) 1.06, 90% interval 0.94 to 1.19.
Homologues: Orthologues: chimpanzee PSMC5 (100% identical), guinea pig PSMC5 (100% identical), macaque PSMC5 (100% identical), mouse Psmc5 (100% identical), pig PSMC5 (100% identical), rat Psmc5 (100% identical), dog PSMC5 (99% identical), zebrafish psmc5 (98% identical), tropical clawed frog psmc5 (97% identical), Drosophila melanogaster Rpt6 (92% identical), Drosophila melanogaster Rpt6R (85% identical), Caenorhabditis elegans rpt-6 (84% identical), and 1 more. Paralogues in human: PSMC1 (46% identical), PSMC2 (44% identical), PSMC4 (44% identical), PSMC3 (44% identical), PSMC6 (43% identical).